FOXA1 (forkhead box A1)
Diseases named in the same sentence as FOXA1 in open-access papers (continued):
Sharing a sentence is not in itself a finding about the gene and the disease.
tumor (continued). "Among patients with a PD-L1 + tumour (N = 145), RFS (p = 0.012) and OS (p = 0.002) were shorter in case of AR/FOXA1 co-expression." (PMID 29880907, 2018). "For example, FOXA1 and FOXA2 cooperate with nuclear hormone receptors in endocrine-driven tumors of the breast, prostate and liver." (PMID 29155818, 2017). "The level of methylation at enhancers with transcription factor binding regions for ERα, FOXA1 and GATA3 appeared central in the regulation of TF target genes involved in tumor response to estrogen." (PMID 29123100, 2017). "High FoxA1 gene expression significantly correlated with high expression of well-established luminal markers, such as GATA3 and ESR1, in primary tumours." (PMID 27045898, 2016). "We further noticed that, although the FOXA1 protein was barely detectable in control H460 H-INV-formed xenograft tumors, a few tumor cells showed positive staining for FOXA1 in xenograft tumors for SAHA-treated H460 H-INV cells." (PMID 27634890, 2016). "We revealed TFs whose expression is linked to a large number of tumor-specific enhancers and further characterized selected TFs for each tumor type (e.g., BRCA: GATA3, FOXA1, ESR1, PRAD: HOXC6, DLX1, KIRC: ZNF395) and for specific tumor subgroups." (PMID 27833659, 2016). "When U-CH1 cells were maintained in hypoxia, we found an increase in the expression of notochord markers (T, CD24, FOXA1, ACAN and CA12), tumour-sphere formation and cell growth, and a decrease in cell migration." (PMID 25541962, 2014). "Luminal A tumours tend to be low grade tumours that are characterised by over expression of ER-activating genes including LIV1, CCND1, FOXA1, XBP1, GATA3 and Bcl-2." (PMID 24392136, 2014). "However, our study found that the FOXA1 level in ECs was significantly higher than that in atypical hyperplasia and normal tissues (p < 0.05) in immunohistochemical specimens and that FOXA1 promoted tumor cell proliferation in EC, which differs from the previous results." (PMID 24512546, 2014). "In the case of BRCA1 vs BRCA2 tumours, only four of the influential TFs (GATA3, ESR1, FOXA1 and XBP1) were identified as differentially expressed." (PMID 25521701, 2014). "FOXA1 and AR immunostainings were positive in 90% and 58% of MA tumors, respectively, and 57% were positive for GCDFP15 with 5% to 90% stained tumor cells (median 50%)." (PMID 23663520, 2013). "Only one CRPC sample harbored a FOXA1 mutation which was isolated from a patient included in the initial exome study, but the DNA used in the targeted sequencing was obtained from a different site suggesting the FOXA1 mutation was a divergent event not seen in the primary tumor." (PMID 23420418, 2013). "We identified the tumor suppressor IGFBP-3 as a novel target of FOXA1, and showed that FOXA1 targeting of IGFBP-3 plays an essential role in regulating PC cell proliferation." (PMID 22879989, 2012). "It should be noted that at least two other genes in the FOXA1 set, TLOC1 and SDCCAG1, are reported to act as tumor suppressors in their own right." (PMID 20731868, 2010). "Spatial transcriptomic data indicated that FOXA1 and SLC7A11 are highly expressed primarily in tumor epithelial and neuroendocrine cells, suggesting that these may be the key cell types through which FOXA1 and SLC7A11 exert their oncogenic roles." (PMID 41330917, 2025). "Importantly, FOXA1 reprograms the AR cistrome in PCa and its overexpression, either alone or in combination with HOXB13, can push the AR towards a more tumor-like cistrome." (PMID 40833121, 2025). "FOXA1-OE did not change primary tumor growth in vivo compared to control mice, whereas HNF4G deletion had a substantial impact on primary tumor growth." (PMID 41168397, 2025). "Intriguingly, FOXA1 and BMI1 exhibit opposing roles in modulating the PI3K/Akt pathway: BMI1 activates PI3K/Akt signaling to drive tumor growth and chemoresistance, whereas FOXA1 suppresses MND1 to inhibit progression and enhance oxaliplatin sensitivity via the same pathway." (PMID 40623983, 2025).
tumor (continued). "Unlike the generally acknowledged tumor suppressor FOXA1, FOXC1 is considered to have dual roles in both oncogenesis and tumor suppression, with its specific behavior depending on its context within the pathway." (PMID 40003882, 2025). "FOXA1 and FOXA2 regulate the hypoxic transcriptional program inversely when PCa is in a hypoxic tumor microenvironment, and which of FOXA1 and FOXA2 tends to regulate HIF1A may depend on the high or low expression of FOXA1 and FOXA2 in the PCa phenotype." (PMID 38605023, 2024). "With integrative analysis of whole genome CRISPR screening data from DepMap Project, GBC RNAseq data, and the Coltron prediction results, five CRC TFs (SOX9, TCF7L2, FOXA1, TGIF1 and HES1) were found to meet all our defined criteria for gene expression and tumor‐dependency levels." (PMID 39492805, 2024). "Luminal tumours were (GATA3, FOXA1+), and basal/squamous tumours were (KRT5/6, KRT14+)." (PMID 39594166, 2024). "FOXA1 and NR3C1 are expressed at fluctuating degree between the different tumor types." (PMID 38015476, 2024). "We found that FOXA1 and FOXM1 were significantly positively correlated with tumor purity in patients with BRCA, while FOXC2, FOXO3, FOXP1, and FOXQ1 were significantly negatively correlated with tumor purity in patients with BRCA." (PMID 38608123, 2024). "FOXA1 exhibits differential expression in numerous tumor samples, with up-regulated expression levels in tumor tissues of CEST, LUAD, BRCA, STAD, PRAD, and PAAD, and down-regulated expression levels in tumor tissues of COAD, KIRP, HNSC, and KICH." (PMID 39440050, 2024). "While some studies suggest that it promotes cell death by regulating genes like FOXA1, Bcl-2, JAK2, and PTEN, others indicate that it might suppress cell death by targeting tumor suppressors like MX1 and TXNIP and influencing ERα signaling." (PMID 39199587, 2024). "Notably, the different regulatory functions of FOXA1 and FOXA2 in tumorigenesis are also substantially different in different sexes and various subtypes of cancer, which can act as oncogenes or tumor suppressors." (PMID 38605023, 2024). "The oestrogen-ERα axis can also play a role in tumour promotion in the absence of Foxa1 and Foxa2 in the receptor complex." (PMID 37752418, 2023). "P4HA2 and PLOD2 are regulated by FOXA1, tumor growth factor-β (TGF-β), and hypoxia-inducible factor-α (HIF-1 α) to induce remodeling of extracellular matrix (ECM) and cancer cell stemness to drive tumor cell invasion and metastasis." (PMID 36826019, 2023). "Reduction in SKP2:FOXA1 indicates that pharmaceutical inhibition of SKP2 is sufficient to target the SKP2–FOXA1 interplay and subsequently increase FOXA1 protein levels, while simultaneously suppressing tumor proliferation." (PMID 37491794, 2023). "Furthermore, MCM3AP-AS1 directly binds to miR-194-5p and promotes the expression of its target gene forkhead box A1 (FOXA1), which was the anti-tumor mechanism of HCC." (PMID 36769116, 2023). "Among them, the target genes of H3K4me3 resulting from FOXA1, GATA3 and PLOR2A as well as H3K27ac resulting from EP300 and GATA3 were significantly enriched in the gene sets (CERES = −2∼−0.4, p < 0.001), signifying a broad dependency for tumor proliferation." (PMID 37876590, 2023). "Therefore, given the dual role of FOXA1 and ZBED2 in the regulation of cell identity and inflammation, it will be important to study their link with tumour plasticity and in response to immunotherapy." (PMID 36944729, 2023). "Interestingly, tumor samples from TKO;NfibR388K and TKO;Carm1KO mice display reduced FOXA1 expression, suggesting the existence of a possible feedback loop." (PMID 36690626, 2023).
tumor (continued). "It is interesting to note that a significant number of mRNAs from the signatures of genes suppressed during EMT, including FOXA1, DSC3, RARRES1, PTEN, and RARRES1, have characteristics of tumor suppressors, including inhibiting hypoxia, tumor cell proliferation, and tumor cell invasion." (PMID 36980175, 2023). "Moreover, instead of FOXA1, these HNF4A+ tumor-specific hypoDMRs were co-enriched for AP-1 factors, which are well-recognized for their function in promoting EAC malignancy, similar to HNF4A itself." (PMID 37620896, 2023). "According to the HPA dataset, the positive rate of FOXA1 expression was high in tumor tissues, whereas all the normal breast tissues were not stained." (PMID 36292640, 2022). "The copy number values were positively correlated with FOXA1 expression, and the methylation levels of the FOXA1 promoter were negatively correlated with FOXA1 expression in most tumor types, while not in EOC." (PMID 36393971, 2022). "FOXA1 and MSX2 were experimentally validated to induce the EMT process and tumor metastasis in other cancers, indicating that FOXA1 and MSX2 may be critical drivers in tumor metastasis of TNBC." (PMID 36291687, 2022). "In summary, miR-4721 acts as a stemness accelerator in addition to its function as a tumor promoter via the miR-4721/FOXA1/Nanog negative feedback loop mechanism." (PMID 34503528, 2021). "Furthermore, many TFs, such as FOXA1 and ESR1, have been shown to contribute oncogenic activity in some cancer types, while acting as tumour suppressors in other contexts, often involving different protein–protein interactions." (PMID 33850167, 2021). "Recently, a role for FOXA1 that is independent of its pioneering function was discovered in the regulation of the tumor immune response." (PMID 34680352, 2021). "Conversely, molecular apocrine tumors, defined as AR- and FOXA1-expressing tumors that frequently harbor PIK3CA mutations, were more frequently associated with a “cold tumor” phenotype (i.e., low TIL density and absence of PD-L1 expression)." (PMID 33673133, 2021). "Furthermore, among patients with PD-L1-positive tumor, poorer relapse-free survival (RFS) and overall survival (OS) were observed in the case of co-expression of AR and FOXA1." (PMID 33915941, 2021). "Conversely, γδ T cell infiltration was not correlated with tumor size, nodal status, histological type, basal-like phenotype, PIK3CA1 mutations, and AR or FOXA1 expression." (PMID 33673133, 2021). "CCK-8 assay showed that FOXA1 suppressed the growth of HK1 cells, whereas transfection of either miR-100-5p or miR-125b-5p rescued tumor cell growth in HK1/FOXA1 cells, indicating that downregulation of miR-100-5p and miR-125b-5p contribute to cell growth inhibition regulated by FOXA1." (PMID 32201519, 2020). "Current literature suggests, however, that regardless of tumor type, FOXA1 is an important cofactor for directing the transcriptional activity of AR." (PMID 33062889, 2020). "Expression of SYP and ENO2 in patients as well as in healthy donors does not relate to any the presence nor malignity of the tumor, while FOXA1 seems to be specific for adenocarconima CTCs." (PMID 32685010, 2020). "It was therefore not possible to evaluate FOXA1 and Nestin expression in the primary tumor at this time." (PMID 30819139, 2019). "Moreover, tumor suppressive lncRNA MT1DP inhibits cell proliferation and colony formation, but induces apoptosis of HCC cell in a FOXA1 dependent manner." (PMID 30782188, 2019). "(F) Expression of the luminal markers, FOXA1 (1.8-fold increase) and GATA3 (1.8-fold increase), and the basal markers, CDH3 (6-fold decrease) and KRT6A (9-fold decrease) in tumor xenografts from mice treated with 5’-azacitidine compared to those of the vehicle control." (PMID 31036156, 2019). "Positive immunohistochemical staining to FOXA1 was also nuclear, and was observed in neoplastic cells as well as scarce tumor-infiltrating lymphocytes (data not shown)." (PMID 31888566, 2019).
tumor (continued). "Notably reduced expression of AT2 markers begins early in tumor development and occurs despite sustained NKX2-1, FOXA1, and FOXA2 expression in tumor cells." (PMID 31452510, 2019). "Concomitant Foxa1/2 deletion at initiation reverses this phenotype, showing that when FoxA1/2 are absent at tumor initiation, NKX2-1-negative lesions equilibrate to a low proliferation state that never progresses to macroscopic disease." (PMID 30475207, 2018). "Coexpression of Forkhead box A1 (FOXA1) with androgen receptor (AR) could be used as a biomarker for the identification of subtypes of TNBC and promotes tumor cell proliferation." (PMID 30175120, 2018). "Interestingly, they found a pro-oncogenic gene expression signature in early neoplasia which was distinct from normal tissues and carcinoma (DCIS/IDC) including up-regulation of ERBB2, FOXA1, and GATA3." (PMID 29720211, 2018). "Several members of this family, such as FOXA1 and FOXP1, may be either oncogenic or tumor-suppressive depending on how they interact with the distinct transcriptional networks of tissue-specific cancers." (PMID 30360388, 2018). "When Nkx2-1, Foxa1 and Foxa2 are deleted at tumor initiation, the resulting lung lesions lacked evidence of either pulmonary or gastric differentiation." (PMID 30475207, 2018). "Our analysis suggested that FOXA1 expression is more important for distinguishing sex non-specific tumors types in female tumor samples than in male samples." (PMID 28673244, 2017). "Moreover, FOXA1, FOXA2, and FOXA3 were also grouped together with the tumor/invasion suppressor genes EPHB2 and EPHB3, and with the intestine-specific differentiation genes CDX1 and CDX2 (cluster 2)." (PMID 29155818, 2017). "Transcriptional profiling classified the Ta tumours as luminal (high expression of luminal markers such as GATA3, PPARG, FOXA1 and XBP1 as well as differentiation markers such as UPK1A and KRT20) as well as non-aggressive (high expression of SKAP2, FABP4, MBNL2 and ID1)." (PMID 28916750, 2017). "In patients with ER-positive tumors, multivariate analysis revealed that AR(-)/FOXA1(-) tumors were independently poor prognostic factors for DFS and OS when age at diagnosis, tumor and node stage, histologic grade, HER2, Ki-67, and use of chemotherapy and endocrine therapy were adjusted." (PMID 29137314, 2017). "Furthermore, the luminal category of tumours frequently express the transcription factors RXRA, PPARG, FOXA1, and GATA3, which are known to have a crucial role in urothelial differentiation." (PMID 28195647, 2017). "For example, FOXA1, MLPH, NAT1, MAPT and BAG1 are expressed in luminal tumours according to published mRNA profiles and also co-clustered in our data, with higher expression levels in most ERPR tumours." (PMID 26725330, 2016). "Lower FoxA1 expression was observed in non-luminal tumours; however, a subset also expressed higher FoxA1 levels." (PMID 27045898, 2016). "In support of this notion, most if not all infiltrating tumor cells showed cytoplasmic Foxa1 staining, which also revealed spindle-type cell shapes conspicuous in EMT." (PMID 26395490, 2015). "Furthermore, we confirmed the regulatory effect of miR-212 on FOXA1, AFP and YAP in xenograft tumor tissue." (PMID 25965836, 2015). "Furthermore FOXA1 and GATA3 are frequently downregulated in basal tumour but rarely over-expressed or amplified in luminal cancer while PBX1 is among the top upregulated genes and is frequently amplified in luminal cancers." (PMID 26215677, 2015). "In fact, FOXA1 and GATA3 showed expression levels up-regulated at least 50% in 19 (86%) and 16 (73%) of 22 patients, respectively, when individual matched normal and neoplasia levels were compared." (PMID 24887547, 2014). "Out of 10 samples with FOXA1 positive NAT, and FOXA1 negative associated tumor, 4 tumors exhibited negative AUM staining, while 6 tumors retained AUM staining." (PMID 22590586, 2012).
tumor (continued). "Basal-like subtype tumours were negative for FOXA1 (B3) and for GATA-3 (B4) in 85.7% and 84.6% of the cases, respectively." (PMID 19549328, 2009). "FOXA1-OE was unable to reverse the tumor growth retardation resulting from the deletion of HNF4G, suggesting that HNF4G is the dominant transcription factor in the primary tumor context, whereas FOXA1 appears to lack any tumor-promoting activity in this context." (PMID 41168397, 2025). "Consequently, the repression of RBM47 may result from a combination of a decrease of FOXA1 expression and the activation of the RBM47-repressing factors, such as STAT3, during tumor progression." (PMID 41335176, 2025). "FOXA1 could bind to active enhancers in PDAC (in primary tumor tissue and the various models) at the same places as HNF4G; we could not observe a role for FOXA1 in mediating chromatin accessibility, gene expression or cell viability in primary tumor contexts." (PMID 41168397, 2025). "To examine whether the REV-ERBα, FOXA1, and BRD4 regulatory axis plays a function in vivo in control of tumorigenic gene programs, we first performed FOXA1 and REV-ERBα ChIP-seq analysis with a PDX tumor model." (PMID 39383000, 2024). "Of interest, six proteins (FOXA1, ERBB2, MAPT, NAT1, PHGDH, KRT5) and one protein (PHGDH) overlapped between PAM50 and the differentially expressed proteins between basal-like and luminal-like subtypes in microdissected tumor epithelium and stroma, respectively." (PMID 37349288, 2023). "Furthermore, ADRB1 genes may act synergistically with FOXA1 and ADRB2 genes to drive tumor formation and development." (PMID 35903112, 2022). "Moreover, its expression was significantly correlated with tumor grading and inversely correlated with the expression of its putative targets, N-acetyltransferase-1 (NAT1) and forkhead box A1 (FOXA1), the presence of which is specific for better outcomes for patients with luminal tumors." (PMID 35163157, 2022). "Notably, FOXA1 expression in A549 cells reduced the efficacy of the anti-angiogenic drug nintedanib to inhibit xenograft tumor growth, whereas a combination of nintedanib with IGF1R inhibitor linsitinib or mTORC1 inhibitor rapamycin enhanced tumor control." (PMID 35974000, 2022). "On the contrary, in other studies, PDL1 expression on tumor cells and on TILs was not significantly different between AR-negative and AR-positive tumors, but a higher rate was observed in the AR-positive and FOXA1-negative subgroups." (PMID 33915941, 2021). "Additionally, accessibility levels across all FOX motifs, irrespective of genomic location, were positively correlated with tumor stage, despite no apparent differences in FOXA1 gene expression levels between tumors of different stages." (PMID 34922480, 2021). "Moreover, FOXA1 suppresses the tumor immune response independent of its licensing function, rendering tumors insensitive to immune checkpoint blockade." (PMID 34680352, 2021). "Interestingly, in our study, relapses could occur even after a long follow-up in patients with AR + /FOXA1 + tumours, like in patients with ER + /HER2- tumours." (PMID 29880907, 2018). "However, in pleural metastases no increase in FOXA1 levels was observed relative to the primary tumor, implicating metastatic site organotropism in relation to FOXA1 levels." (PMID 29972720, 2018). "Moreover, in clinical samples from male HCC patients, FOXA1 expression was much lower, whereas PI3Kp85 levels were much higher in tumor than in non-tumor tissues." (PMID 29208003, 2017). "Interestingly, MDA231 triple negative-like cells expressed high levels of FoxA2 but not FoxA1, and the non-tumour HMECs did not express these factors." (PMID 27045898, 2016).